ESR1 (estrogen receptor 1)
Diseases named in the same sentence as ESR1 in open-access papers (continued):
Sharing a sentence is not in itself a finding about the gene and the disease.
osteoporosis (continued). "The 5 genes (AXL, GAB1, ERBB2, NRP2, and ESR1) along with 13 pharmacological agents represent promising candidates for enhancing the treatment of osteoporosis and sarcopenia." (PMID 40660573, 2025). "The identification of EGFR, ESR1, and SRC as key regulatory hub genes provides valuable insight into the potential molecular mechanisms underlying PPIs-induced osteoporosis." (PMID 40421218, 2025). "Estrogen receptor 1 (ESR1) is located on chromosome 6q25, is a sex steroid associated with the occurrence of osteoarthritis and osteoporosis, which plays a critical role in skeletal muscle homeostasis and motor function." (PMID 39156961, 2024). "Several large GWAS have investigated the genetics of osteoporosis, revealing BMD-associated genes, including ESR1, LRP4, ITGA1, LRP5, SOST, SPP1, TNFRSF11A (RANK), TNFRSF11 (RANKL), and TNFRSF11B (OPG)." (PMID 39769358, 2024). "To date, several genome-wide association studies (GWASs) have found hundreds of candidate genes associated with osteoporosis, including RANKL, SOST, ESR1, PTHLH, and DKK1." (PMID 37683138, 2023). "Thirdly, we elucidated a novel role of UF as a protector against osteoporosis by activating the ESR1/β-catenin pathway." (PMID 35956385, 2022). "Several single nucleotide polymorphisms (SNPs), such as estrogen receptor α gene (ESR1) and major histocompatibility complex gene (MHC), were associated with age of natural menopause and possible subsequent osteoporosis." (PMID 35163300, 2022). "The polymorphism at the ESR1 site affects the development process of POF, among which the polymorphism at the PvuII (rs2234693) site can induce many complications, such as osteoporosis and cardiovascular disease." (PMID 35003302, 2021). "Previous studies revealed that two polymorphisms of ESR1 (estrogen receptor 1) (rs9340799 and rs2234693) are associated with the BMD response to raloxifene in osteoporosis patients." (PMID 32934756, 2020). "Of these, only ESR1 and LRP5 have shown to be effectively contributing to explain population variance in risk for osteoporosis." (PMID 33162933, 2020). "Several candidate genes, such as ESR1, the major mediator of estrogen action in bone, have been reported to be associated with BMD and osteoporosis." (PMID 32493284, 2020). "It is therefore conceivable that the perturbation of FOXA1 dimers or of related forkhead TFs on the rs2941742 locus modifies ESR1 regulation and contributes to the etiology of osteoporosis." (PMID 29669022, 2018). "Oestrogen action in bone are mediated mainly through ERα codified by the ESR1 gene, which has been associated with different osteoporosis related traits in previous studies." (PMID 28974197, 2017). "A genome-wide association study (GWAS) reported that five SNPs in the ESR1 gene exhibited an association with BMD of both the hip and spine, suggesting a possible role for the ESR1 gene in the pathogenesis of osteoporosis." (PMID 25978039, 2015). "On the other hand, the correlation between serum markers (e.g. CASP3, ESR1) and bone mineral density in the smoking population can be analyzed in conjunction with clinical cohort studies to assess the potential clinical effects of nicotine on osteoporosis." (PMID 41568086, 2026). "In addition, bone-protective drugs based on ESR1/ CASP3 dual targets should be explored to further evaluate their application prospects in osteoporosis prevention and treatment." (PMID 41568086, 2026). "ESR1 is important in osteoporosis because of its role in bone growth and maintenance." (PMID 40772209, 2025). "In the present study, we tested the estrogenomimetic effects of ICT, and confirmed the pharmacological effects of ICT on inhibiting osteoclast differentiation and anti-osteoporosis through in vivo and in vitro, and the expression of ESR1, ESR2 and miR-503 in OC was assessed." (PMID 41019997, 2025). "Therefore, the aim of the present study is to investigate the association between ESR1 polymorphism and MRONJ occurrence in osteoporosis patients taking BPs." (PMID 37415765, 2023).
osteoporosis (continued). "Moreover, 17β-estradiol is reported to play an anti-osteoporosis role via a novel ESR1-Keap1-Nrf2 axis-mediated regulation." (PMID 38256321, 2023). "Integrated “herbs-compounds-targets” network and KEGG pathway analysis predicted that BYD might possess its anti-osteoporosis effect on PMOP via the activation of ESR1 and estrogen signaling pathway." (PMID 34045964, 2021). "Interestingly, ESR1 is a gene relevant for bone metabolism as osteoporosis mainly affects post-menopausal women with depressed levels of its activating ligand estrogen." (PMID 29669022, 2018). "Moreover, ESR1 rs2234693 genotypes correlated with family history of osteoporosis (FHO) and hip fracture (FHF) (P < 0.01), while ESR2 AA-AC genotypes were strongly associated with FHF (OR 2.387, 95% CI 1.432–3.977; P < 0.001)." (PMID 19386104, 2009). "Furthermore, they detected a joint effect of ESR1 gene in osteoporosis modulating the penetrance of ESR2 rs4986938 genotype." (PMID 19386104, 2009). "The ESR1 gene PvuII and XbaI TA (px) haplotype correlated with decreased femoral neck T-score (OR = 2.75, CI = [1.21–6.27], P-value = 0.016) and may be predictive of osteoporosis in female patients with CD." (PMID 31450614, 2019). "We aim to investigate the impact of estrogen receptor gene (ESR1) gene polymorphisms on bone mineral density (BMD) in patients with ulcerative colitis (UC) and Crohn’s disease (CD), as they may contribute both, to osteoporosis and inflammatory processes." (PMID 31450614, 2019). "This study identified EGFR, ESR1, and SRC as key regulatory genes in PPIs-induced osteoporosis, highlighting their roles in bone metabolism." (PMID 40421218, 2025). "We identified EGFR, ESR1, and SRC as key regulatory hub genes, suggesting their crucial roles in bone metabolism and the development of osteoporosis." (PMID 40421218, 2025). "In one GWAS, key genes involved in osteoporosis were TNFRSF11B (OPG), TNFSF11 (RANKL), LRP5, and ESR1." (PMID 40772209, 2025). "After screening the core therapeutic ingredients, a PPI network was constructed to determine core targets; our results showed that AKT1, CASP3, EGFR, ESR1, IGF1, MAPK1, and MAPK14 are important for AB–DA treatment of osteoporosis." (PMID 37849727, 2023). "Further bioinformatic analysis revealed 8 core targets (EGFR, AR, ESR1, MAPK8, MDM2, EZH2, ERBB2 and MAPT) in the VitD-COVID-19-osteoporosis network." (PMID 36307516, 2022). "According to topological analysis results, AKT1, MAPK1, ESR1, and SRC are critical genes for RRP to treat osteoporosis, and they have high binding activity with stigmasterol and sitosterol." (PMID 34649566, 2021). "They localize to distal enhancer of ESR1 and MAPT genes, which are related to osteoporosis or Parkinson's disease, respectively." (PMID 29669022, 2018). "By the comparison of gene chips from five osteoporosis patients and four normal samples of bone marrow stem cell, we identified genes (IL17RC, COL1A1, and ESR1) that directly interact with the OPG gene." (PMID 23731710, 2013). "The osteoporosis candidate genes transforming growth beta 1 (TGFB1) and estrogen receptor alpha (ESR1) are both localized within this locus." (PMID 21818327, 2011). "Therefore, ESR1 is a direct target of the inhibitory effect of ICT on osteoclast differentiation and anti-osteoporosis." (PMID 41019997, 2025). "The identification of ESR1, NRP2, AXL, ERBB2, and GAB1 as key genes provides novel therapeutic targets and highlights the importance of understanding shared molecular pathways in osteoporosis and sarcopenia." (PMID 40660573, 2025). "The sample sizes for four gene loci, namely, COL1A1 1245GT (rs1800012), IGF1 (rs5742612), IL6 G174C (rs1800795), and ESR1 XbaI (rs9340799), were sufficient for a conclusion of noncorrelation with osteoporosis." (PMID 35452412, 2022). "Regarding family history of osteoporosis (FHO) and of hip fracture (FHF), no significative association was found with single or combined analysis of ESR1 polymorphisms." (PMID 19386104, 2009).
osteoporosis (continued). "Family history of osteoporosis (FHO) and of hip fracture (FHF) regarding ESR1 and ESR2 genotypes." (PMID 19386104, 2009). "In addition, we have found a genetic interaction of NRIP1 gene with Estrogen receptor alpha and beta (ESR1 and ESR2) genes in two estrogen-dependent diseases such as male infertility and osteoporosis (manuscript in preparation)." (PMID 16131398, 2005). "More cases were required for the remaining six gene loci, namely, ESR1 PvuII (rs2234693), VDR ApaI (rs7975232), VDR BsmI (rs1544410), COL1A1 1997GT (rs1107946), ESR1 G2014A (rs2228480), and ESR2 AluI (rs4986938), before a definite conclusion could be made on their correlation with osteoporosis." (PMID 35452412, 2022). "Also, ESR1-deletion mice showed a phenotype of TNF-α regulation and spontaneous osteoporosis, suggesting that the ESR1 could be a major target in PMOP treatment." (PMID 34045964, 2021). "For ESR1 and ESR2, two genes worldwide evaluated by independent research groups, the results obtained even if compelling for their involvement in BMD, osteoporosis, or fracture, are, however, not conclusive." (PMID 19386104, 2009). "It is suggested that ESR1, rather than ESR2, may serve as the primary target of ICT, and it has been proposed that ESR1, but not ESR2, plays a pivotal role in osteoclast differentiation and osteoporosis." (PMID 41019997, 2025).
endometriosis (233 papers, 2006 to 2026). The growth of functional endometrial tissue in anatomic sites outside the uterine body. "The results suggest that further, well-designed, large-scale studies are needed to shed light on the problem of ovarian cancer formation due to endometriosis in correlation with ESR1 polymorphisms." (PMID 40429755, 2025). "Preliminary genomics studies have found associations between endometriosis and polymorphisms in the ESR1 and CYP17A1 genes." (PMID 41323407, 2025). "Dysregulation of the ESR2/ESR1 ratio in ectopic endometrial stromal cells has been implicated in endometriosis pathogenesis and disease severity." (PMID 40072055, 2025). "ESR1 was positively associated with endometriosis in 19 endometrial cellular contexts, and mSMR returned causal CpG site associations with intron-dependent effect directions." (PMID 41377979, 2025). "Of these, variants on chromosome 6 near ESR1 have been associated with endometriosis and various other reproductive traits and diseases." (PMID 41464345, 2025). "Lastly, a recent study has discovered that depression and five reproductive endocrine illnesses, such as UFs and endometriosis, share a common genetic variant known as ESR1." (PMID 38890689, 2024). "Genome-wide association studies have reported that the early age of menarche is associated with SNVs at several gene loci, including ESR1 and that candidate genes for the age of menarche are associated with an increased risk of developing endometriosis." (PMID 39200122, 2024). "Overall, we have shown that rs2046210 is genetically predisposed to low-grade endometriosis, particularly in younger, leaner and infertile women, and can contribute to changes in the levels of endometrial ESR1 expression." (PMID 39200122, 2024). "Several endometriosis-risk SNVs at this locus were also identified as drivers of ESR1 expression in endometriosis tissue and blood." (PMID 39200122, 2024). "This genetic case–control study evaluated the association of three SNVs with endometriosis risk and with the regulation of the levels of ESR1 expression in the eutopic endometrial tissue of women with and without endometriosis." (PMID 39200122, 2024). "Oestrogen Receptor 1 (ESR1), a transcription factor important for hormone binding, was associated with endometriosis, uterine fibroids and depression." (PMID 37159502, 2023). "The true signals in the region of ESR1 associated with endometriosis risk are the non-coding variants located in intergenic regions flanking ESR1." (PMID 33806348, 2021). "Variation within the estrogen receptor gene ESR1 has been linked to endometriosis susceptibility and maternal age at first birth." (PMID 33466305, 2021). "To date, the genetic risk factors for endometriosis-related infertility have also included the ESR1, ESR2, and luteinizing hormone beta-subunit FOXP, complement component 3, lysyl oxidase-like protein 4, and FCRL3 genes." (PMID 28405865, 2017). "To date, the genetic risk factors for endometriosis-related infertility have included the 17β-hydroxysteroid dehydrogenase type 1, ESR1, ESR2, and luteinizing hormone beta-subunit genes." (PMID 23553198, 2013). "Therefore, in this study, we aimed to analyze the association of rs2046210, rs9383590 and rs9340799 with endometriosis, and their effect on the regulation of the levels of ESR1 expression in the eutopic endometrial tissue of women with and without the disease." (PMID 39200122, 2024). "Endometriosis also causes hypermethylation in the promoter regions of the PR (progesterone receptor) and ESR1 (estrogen receptor 1) genes, which are essential for steroid hormone signaling and endometrial function, reducing their expression and impairing endometrial receptivity." (PMID 39311136, 2024).
endometriosis (continued). "The heterozygous rs2046210 GA genotype was associated with significantly increased endometriosis risk, particularly in younger, leaner and infertile women and with an increased ESR1 gene expression in the eutopic endometrium of these patients, compared to controls." (PMID 39200122, 2024). "Additionally, the ESR1 rs9340799 GG genotype was associated with a 4-fold increased risk of endometriosis and a 3-fold increased risk of IVF failure in infertile patients." (PMID 37239044, 2023). "As reported, genetic variants in ESR1 were reported to change the susceptibility to endometriosis and might influence the fertility status in endometriosis patients." (PMID 37033258, 2023). "A meta-analysis suggests that this polymorphism in the ESR1 gene may be associated with stage I–III endometriosis." (PMID 37676242, 2023). "Moreover, progesterone receptor expression levels are lower in women with endometriosis associated-infertility, whereas estrogen receptor 1 (ESR-1) levels are increased in the mid- secretory phase endometrium of these women compared to controls." (PMID 36387918, 2022). "A similar GWAS study aiming at identifying gene of reproductive behaviour failed as well to be found in common as at risk for endometriosis, albeit GATAD2B and ESR1 were found as most likely causal and are indeed increased in expression in endometriosis lesions compared to the eutopic endometrium." (PMID 34298916, 2021). "We strongly believe that the present method could be used to study ESR1 mutations in patients with cervical cancer and endometriosis." (PMID 33535614, 2021). "This led us to hypothesize that the downregulation of ESR1 in endometriosis is caused by aberrant DNA methylation of these T-DMRs." (PMID 30728052, 2019). "Conditional analyses identified five novel secondary association signals at these implicated loci, including two at the ESR1 locus, resulting in a total of 19 independent SNPs robustly associated with endometriosis, which together explain up to 5.19% of variance in endometriosis." (PMID 28537267, 2017). "Recent large-scale GWASs of endometriosis have shown that single-nucleotide variants (SNVs) at 42 loci are associated with endometriosis risk at a genome-wide significance, with five association signals found in chromosomal region 6q25.1, which contains the ESR1 gene." (PMID 39200122, 2024). "In addition, the downregulation of ESR1 in endometriosis could be caused by an aberrant DNA methylation of a specific region of the gene called the tissue-dependent and differentially-methylated-region (T-DMR)." (PMID 32316608, 2020). "According to the most recent studies, the following genes may account for the potential risk factors of infertility associated with endometriosis: ESR1, ESR2, beta hormone luteinizing gene, FOXP subunit, complement component 3 gene, and the Fc receptor-like 3 (FCRL3) gene." (PMID 33153202, 2020). "Conditional analysis identified five secondary association signals, including two at the ESR1 locus, resulting in 19 independent single nucleotide polymorphisms (SNPs) robustly associated with endometriosis, which together explain up to 5.19% of variance in endometriosis." (PMID 28537267, 2017). "There were three stromal cellular contexts in which the expressions of RSPO3, WNT4, and ESR1 were significantly different depending on endometriosis status." (PMID 41377979, 2025). "The expression of genes with critical roles in hormonal regulation (ESR1, PGR, GREB1) has also been implicated in endometriosis." (PMID 41464345, 2025). "The ERα downregulation in endometriosis has been reported to be attributable to ERβ overexpression that suppresses ESR1 expression since the ERβ protein binds to the ESR1 gene promoter." (PMID 40521103, 2025). "Among the subjects with the GA genotype and an age ≤ 35 years, the levels of ESR1 expression in endometriosis patients were 4.66-fold higher (adjp = 0.0171) than in the controls." (PMID 39200122, 2024).